TFF3 (trefoil factor 3)
Diseases named in the same sentence as TFF3 in open-access papers (continued):
Sharing a sentence is not in itself a finding about the gene and the disease.
tumor (124 papers, 2003 to 2026). "Conversely, SOX4 also acts as an oncogene, and TFF3 as a potential tumor suppressor, both linked to OS." (PMID 41646983, 2026). "The quantity and intensity of cellular interactions among PGA3+ tumor cells in cluster 0, MUC5AC+ tumor cells from cluster 1, TFF3+ tumor cells associated with cluster 2, and other diverse cell types were then illustrated." (PMID 40124374, 2025). "In contrast, C1 and C3 exhibited overexpression of trefoil factor family genes (TFF1, TFF2, and TFF3), which are associated with angiogenesis, apoptosis, and tumour progression." (PMID 37994257, 2024). "Six sex-specific, Esr1-dependent transcripts–A1bg, Fmo3, Cabyr, Cspg5, Mthfd1l, Tff3–are strongly implicated in hepatocarcinogenesis based on their expression, prognostic power, or oncogenic/tumor suppressive properties." (PMID 34068249, 2021). "Tff3 was linked to oxidative stress in human tumor cells, where it was upregulated in the late phase of response to oxidative stress caused by X-rays." (PMID 31500117, 2019). "We performed a lentiviral overexpression of TFF3 in Y79 RB cells and analyzed different potential target genes involved in TFF3 signaling to investigate the underlying mechanisms of TFF3’s tumor-suppressive functions." (PMID 31450568, 2019). "They found also that the levels of TFF3 expression in the primary tumor were associated strongly with its level in the corresponding metastatic cells and the level was increased as the tumor cells moved along the metastatic cascade from the primary tumor." (PMID 29977293, 2018). "TFF3 overexpression is implicated in tumor invasion and in limiting tumor cell death in many cancers, including PCa." (PMID 30139961, 2018). "Elevated levels of TFF3 protein were observed to be associated with advanced clinicopathological features of disease, such as tumour size, higher disease grade and metastases." (PMID 29100386, 2017). "In this study, we report that higher TFF3 expression in HCC patient samples is associated with larger tumor size, advanced tumor grade, and a higher proliferation index as well as a poor patient survival outcome." (PMID 28445151, 2017). "We next determined potential associations between TFF3 expression in MC and the clinicopathological characteristics of the tumour cohort." (PMID 25266665, 2014). "The change in IGFBP5, TFF3 or both was significantly associated with change in tumor volume (P = 0.0135, 0.018 and 0.0002, respectively; Spearman rank test)." (PMID 20569502, 2010). "Indeed, TFF3 has been reported to be overexpressed at the gene and the protein level in human neoplasms and associated with poor prognosis." (PMID 35461390, 2022). "TFF3 expression in HCC has also been observed to be associated with higher tumor grade." (PMID 28445151, 2017). "Furthermore, Cox regression analyses demonstrated a significant association of tumour TFF3 expression with decreased RFS (P = 0.041) and OS (P = 0.030)." (PMID 25266665, 2014). "A cluster enriched for genes associated with the luminal/ER+ tumor subtypes (N-acetyltransferase 1, estrogen receptor 1, putative G-protein-coupled receptor, trefoil factor 3, GATA binding protein 3, and X-box binding protein 1) was also present in this gene set." (PMID 17150101, 2006). "PPI analysis indicated that the levels of the mRNAs encoding RBPJ, SKP1, CTNNB1, CDH2, SCG2, VGF, and TFF3 were significantly increased in PanNEN tumor tissues compared with the matched paratumor tissues and may be involved in the DNER signaling pathway in PanNENs." (PMID 33329729, 2020). "Our analysis of non-tumor cells, such as T cells, NK cells, and B cells, also identified TFF3 as a consistent predictive biomarker for favorable outcomes with CDK4/6is." (PMID 39955556, 2025). "This panel of genes includes trefoil factor family proteins, TFF1 and TFF3, which have been shown to be upregulated in BL immunohistochemistry tumor samples from patients with HR+/HER2- mBC who experience late progression on CDK4/6i therapy." (PMID 39955556, 2025).
tumor (continued). "These tumours frequently retained positive staining for MUC-1, MUC-2, SATB2 and TFF-3, suggesting that these tumours maintain some degree of intestinal differentiation." (PMID 40935920, 2025). "For instance, TFF3 has been associated with epithelial regeneration and cancer metastasis, and KLF4 is known for its dual role in tumor suppression and promotion depending on the cellular context." (PMID 41284725, 2025). "We first detected TFF protein expression in our iCCA cohort using IHC staining with the TFF3 antibody, which confirmed the prominent distribution of TFF3 in the tumor region compared with the normal biliary tract." (PMID 39256888, 2024). "We assumed that the malignant iCCA cells promoted the recruited macrophages towards a tumor-permissive direction by secreting TFF3 proteins." (PMID 39256888, 2024). "The protein trefoil factor 3 (TFF3) secreted by the malignant subclone can induce macrophages to reprogram to a tumor-promoting state, which in turn contributes to an immune-suppressive environment and boosts tumor progression." (PMID 39256888, 2024). "Notable genes displaying similar expression patterns in AFCs and tumour cells compared with FCs included TFF3 and TG (signature genes of FCs), IGHG4 and SFRP2 (signature genes of FCs) and FN1 and SFTPA1 (signature genes of tumour cells)." (PMID 38426403, 2024). "Tumor vascular permeability can be increased to some extent in the extracellular matrix were degraded under the action of TFF3 and VEGF." (PMID 38773485, 2024). "In summary, our data help clarify the mechanisms of tumor-macrophage interaction and offer new perspectives for targeting TFF3 in iCCA treatment." (PMID 39256888, 2024). "TFF3 is able to directly modulate the multiplication cycle on tumor cells, which can promote tumor growth, invasion, angiogenesis and even metastasis." (PMID 38773485, 2024). "TFF-3 has been reported to be overexpressed both as a gene and as a protein in human neoplasms, including intestinal, pancreatic, and prostate cancers and be involved in gastric cancer progression." (PMID 35461390, 2022). "The expression of genes encoding mucins (MUC1, MUC2 and MUC5A) or involved in mucosa protection (TFF1 and TFF3) were positively correlated with AGR2 expression in most tumour types." (PMID 35857928, 2022). "In contrast, the proportion of a TFF3-expressing TEC population with features of high endothelial venules was markedly increased in tumour and its retention correlated with poor response to chemotherapy." (PMID 36253784, 2022). "It was shown that LINC00160‐siRNA tumours had less anti‐TFF3 immunostaining and anti‐Ki67 immunostaining than scramble siRNA tumours." (PMID 32652877, 2020). "Many of the genes upregulated in these tumor initiating cells were expressed in our Cluster 1 cells including Tff3, Tspan8, Gpc3, Ly6d, Cldn2." (PMID 33173221, 2020). "Accumulating evidence has supported the oncogenic functions of trefoil factor 3 (TFF3) in promoting tumor progression." (PMID 31685806, 2019). "Reduction of serum TFF3 levels and tumour expression of TFF3 by AMPC was accompanied by decreased expression of the proliferative marker Ki67 in both the doxorubicin sensitive and resistant ER+MC xenografts." (PMID 31658702, 2019). "The TCGA cohort demonstrated that patients within the CMS4 subtype with low tumour expression of TFF3 exhibited a greater 10-year overall survival outcome compared to patients with high tumour expression of TFF3." (PMID 31835445, 2019). "Along with the protein depletion confirmed by the immunochemistry assay, we confirmed the loss of expression of MLH1 at the RNA level, as well as the upregulation of EPCAM and TFF3 in tumor cells, which are known to be overexpressed in cancer cells." (PMID 31829268, 2019). "As observed, a greater reduction in both the in vitro cell viability and in vivo tumour burden was evident in doxorubicin resistant ER+MC as compared to doxorubicin sensitive ER+MC following the inhibition of TFF3 by AMPC." (PMID 31658702, 2019).
tumor (continued). "Especially the function of TFF3 is controversially discussed as it is considered as a potential oncogenic factor or a tumor suppressor gene depending on the tissue investigated." (PMID 31450568, 2019). "Based on the role of TFF3 in tumor cell survival and metastasis, we rationally designed a small-molecule inhibitor of TFF3, AMPC, specifically to bind to Cys57 of TFF320." (PMID 31685806, 2019). "We also have identified a significant reduction in apoptotic bodies in residual tumor together with high expression of TFF3 suggesting a possible antiapoptotic role of TFF3 in incomplete pathological response group." (PMID 30744593, 2019). "Recently, over-expression of TFF3 was found in spontaneous and carcinogen-induced HCC of mice model or tissues of HCC patients and associated with higher tumor grade." (PMID 30424721, 2018). "Trefoil factor 3 (TFF3) is a novel secretory protein and plays an important role in tumor genesis and immunity." (PMID 30424721, 2018). "The analysis of patients with high TFF3 mRNA concentrations revealed that 68.8% and 56.3% had ER and PR positive primary tumor, respectively." (PMID 29977293, 2018). "There was a strong positive correlation between estrogen receptor and TFF3 protein expression in tumor tissue." (PMID 29977293, 2018). "Blocking the overexpression of TFF3 in two PCa cell lines limited tumor cell growth and migration, and increased cancer cell death." (PMID 30139961, 2018). "The mean TFF3 IHC score in the tumor tissues was significantly higher than that in the normal tissues (4.702 vs. 0.311, P = 2.52 × 10-24)." (PMID 30139961, 2018). "A positive correlation of TFF3 expression with larger tumor size (p < 0.05), advanced tumor stage (p < 0.001) and higher labeling of Ki67 (proliferation index) (p < 0.001) was observed." (PMID 28445151, 2017). "Next, we performed immunohistochemistry (IHC) analysis for TFF3 on resected tumours generated using Ishikawa-vector or Ishikawa-TFF3 cells." (PMID 29100386, 2017). "Detection of TFF1 and TFF3 mRNAs in peripheral blood has been proposed as a surrogate measure of circulating tumor cells." (PMID 28687783, 2017). "The percentage of HCC specimens that showed positive TFF3 staining (55.8%) was approximately twice that of adjacent non-tumor liver tissues (28.2%, p < 0.01)." (PMID 28445151, 2017). "Concordantly, TFF3 expression in EC tumour samples positively correlated with the levels of SP1, and the activity and levels of phospho c-JUN." (PMID 29100386, 2017). "Tumours generated from Ishikawa-TFF3 cells exhibited markedly increased expression of TFF3 compared to tumours generated from Ishikawa-vector cells indicative of phenotypic retention." (PMID 29100386, 2017). "Increased expression of TFF3 has previously been detected in HCC specimens and associated with tumor size and stage, providing evidence for the clinical significance of TFF3 expression in HCC." (PMID 28445151, 2017). "In relation to cancer, TFF3 has been proposed to function both as an oncogene and as a tumor suppressor." (PMID 28930171, 2017). "Consistent with in vitro data, the depletion of TFF3 resulted in attenuated tumor growth of Hep3B-siTFF3 cell-derived xenograft as compared to Hep3B-siVec cell-derived xenograft." (PMID 28445151, 2017). "We further determined the effect of TFF3 on tumour cell proliferation and apoptosis in vivo using Ki67 staining and TUNEL assay respectively." (PMID 29100386, 2017). "In this context, one must, however, be aware of a potential pro-migratory effect of TFF3 in some tumor entities and thus routinely follow up on the formation of metastases." (PMID 27626280, 2016). "In tumours with stronger TFF3 expression, expression was distributed relatively evenly throughout the tumour, whereas in other tumours, expression was strong in some areas and undetectable in others." (PMID 25900183, 2015).
tumor (continued). "TFF3 expression was higher in the tumours of women who responded to endocrine therapy than in those of women who received no benefit (P=0.000, Mann–Whitney U test, Z=−4.940)." (PMID 25900183, 2015). "The angiogenic and metastatic actions of TFF3 therefore regulate tumor progression and dissemination of cancer cells." (PMID 26559818, 2015). "Strong immuno-reaction was detected in the cytoplasm of malignant breast epithelial cells of tumours that expressed high concentrations of TFF3 mRNA (tumours 1, 3 and 15)." (PMID 25900183, 2015). "Increased TFF3 expression in MCF-7 cells has been demonstrated to enhance tumor growth in xenograft models." (PMID 26559818, 2015). "Regardless of the discrepancies in the histopathological analyses and between tumours of different organ origin, we have demonstrated that TFF3 is a functional promoter of metastatic dissemination of MC cells." (PMID 25266665, 2014). "Our data demonstrated that serum TFF3 can be applied as an effective biomarker for the detection of tumor stages and distant metastasis and pharamcodynamic marker of responses to chemotherapy in gastrointestinal cancer." (PMID 25031551, 2014). "In summary, our data indicated that serum TFF3 can be applied as an effective biomarker for the detection of tumor stages and distant metastasis and as a pharamcodynamic marker of responses to chemotherapy in gastrointestinal cancer." (PMID 25031551, 2014). "We observed that patients with tumour expression of TFF3 exhibited significantly poorer RFS (P = 0.036) and OS (P = 0.025) compared to those patients whose tumours express no or low TFF3." (PMID 25266665, 2014). "The secreted protein TFF3 has malignant characteristics to promote the invasion of tumor cells by acting both directly on malignant cells and indirectly on the vasculature." (PMID 25031551, 2014). "The TFF1 and TFF3 genes have been poorly studied regarding detection of circulating tumor cells in cancer patients." (PMID 24058517, 2013). "The changes observed in the expression of IGFBP5 and TFF3 correlated with reductions in tumor volume in primary tumors treated with tamoxifen." (PMID 20569502, 2010). "Trefoil factor 3 (TFF3), located at 21q22.3, belongs to afamily of small mucin-associated polypeptides that can regulate cancer progressionby increasing tumor metastasis." (PMID 21079744, 2010). "In this regard, TFF3 has been shown to regulate cancer progression by increasing tumour metastasis acting as anti-apoptotic, scattering, pro-invasive, and angiogenic agent on cancer cells." (PMID 18682706, 2008). "Trefoil factor 3 staining in tumour tissues appeared to be moderate/strong (total score 2/3) in 40% of cases." (PMID 18682706, 2008). "TFF3 is commonly expressed in hepatocellular carcinoma and its expression correlates with tumor grade." (PMID 19662225, 2007). "TFF3 and the essential tumor angiogenesis regulator VEGF exert potent pro-invasive activity through STAT3 signalling in human colorectal cancer cells." (PMID 19662225, 2007). "TFF3 mRNA expression was distinctly higher in tumor tissues than in peri-tumor tissues." (PMID 41551914, 2026). "This subgroup may have important implications for tumor biology, as TFF3 is known not only for its role in mucus stabilization but also for promoting epithelial restitution and potentially stimulating tumor growth." (PMID 41002393, 2025). "By targeting TFF3, it may be possible to hinder tumor development by influencing the tumor microenvironment." (PMID 40636286, 2025). "TFF3 and pBAD are emerging as important targets in several malignancies including mammary, lung, liver, pancreatic, colorectal, ovarian, and endometrial due to their roles in tumor growth and treatment responses." (PMID 40636286, 2025). "Furthermore, TFF3 has been found to be a leading factor in cancer, contributing to cellular proliferation, evasion of apoptosis, tumor invasion, and the formation of new blood vessels." (PMID 38256434, 2024).
tumor (continued). "The high and correlated expression of CA12 and TFF3 in estrogen receptor-positive BC may play a role in reducing the tumor’s sensitivity to chemotherapy drugs such as adriamycin and docetaxel, which in turn can negatively impact the efficacy of NAC." (PMID 37996875, 2023). "In addition, forced expression of TFF3 significantly promoted the spheroid formation and the tumor-initiating capacity of Capan-1 cells, whereas depletion of TFF3 in SW1990 cells significantly impaired these properties." (PMID 35332126, 2022). "In addition, it was observed that ICG-001 treatment abrogated the enhanced spheroid formation and tumor-initiating capacities of Capan-1 cells with forced expression of TFF3." (PMID 35332126, 2022). "It was observed that TFF3 expression was not related to gender, age, or histological grade, but was significantly associated with tumor size." (PMID 35332126, 2022). "Although aberrant expression of TFF3 has been reported for a variety of tumors, data on its specific role depict it as a molecule acting in a tumor type- or context-dependent manner; more importantly, the receptor for TFF3 has not been discovered or validated, yet." (PMID 35216615, 2022). "In light of this, TFF3 may play a role in regulating cancer progression by increasing tumor metastasis by promoting anti-apoptosis, pro-invasive and angiogenesis agents." (PMID 35461390, 2022). "Tumor progression was increased significantly in mice injected with HCT-8 overexpressing TFF3." (PMID 34262017, 2021). "Furthermore, TFF3 expression correlates with the tumor grade in hepatocellular carcinoma and is a marker for poor prognosis in gastric carcinoma." (PMID 31450568, 2019). "In our study, genes, such as GATA3, ERBB4, RET, NAT1, and TFF3, typically more expressed in ER positive tumor samples, were also more expressed in stromal cells from ER positive as compared with ER negative tumors (defined by immunohistochemistry of malignant cells)." (PMID 31817155, 2019). "Consistent with in vitro results, AMPC treatment significantly reduced tumour and serum TFF3 levels, indicating that serum TFF3 could be used as a response marker to monitor the efficacy of AMPC treatment." (PMID 31835445, 2019). "There was very low or no expression of ki67 protein in residual tumor as compared to high expression of TFF3 in residual tumor cells suggesting that residual tumor cells have a low proliferating activity, this is supported by the high expression of Bcl2 and p-AKT-1 by residual tumor cells." (PMID 30744593, 2019). "TFF3-silenced cells showed suppressed tumor cell growth and migration." (PMID 30139961, 2018). "Moreover, the mean TFF3 IS in the tumor tissues was significantly higher than that in the normal tissues (4.702 vs. 0.311, P = 2.52 × 10-24)." (PMID 30139961, 2018). "Thus, forced expression of TFF3 in immortalized-HMECs stimulates an oncogenic phenotype with tumour formation in vivo." (PMID 30451834, 2018). "Forced expression of TFF3 in immortalized-HMECs enhanced cell proliferation, cell survival, anchorage-independent growth, produced highly disorganised three-dimensional (3D) acinar structures and generated tumours in immunocompromised mice." (PMID 30451834, 2018). "The percentage of the TFF3-positive cell population in Ishikawa-TFF3 cell-derived tumours was significantly higher (84.63±5.82% vs 14.86±3.08%, p value <0.001) as compared to Ishikawa-vector cell-derived tumours." (PMID 29100386, 2017). "Therefore, TFF3 promotes xenograft growth of Ishikawa cells by increasing tumour cell proliferation and reducing tumour cell apoptosis." (PMID 29100386, 2017). "As the metastatic process also involves the adhesion of tumour cells to, and invasion through, the surrounding extracellular matrix, we investigated the effect of TFF3 on the ability of EC cells to adhere to collagen I, which is a major component of the stromal matrix." (PMID 29100386, 2017).